FLI1 (Fli-1 proto-oncogene, ETS transcription factor)
Diseases named in the same sentence as FLI1 in open-access papers (continued):
Sharing a sentence is not in itself a finding about the gene and the disease.
cardiomyopathy (1 paper, 2022). A disease of the heart muscle or myocardium proper. "We have previously demonstrated that the Fli1 pathway is a predominant form of profibrotic signaling in the animal model of cardiomyopathy and that Fli1-dependent signaling can be activated by MBG." (PMID 35562955, 2022).
chlamydial infection (1 paper, 2024). "For example, we demonstrated that simultaneous knockdown of ct226, ct225, and ct224 resulted in a complete loss of localization of either FLI1 or LRRF1 during chlamydial infection and only individual complementation of Ct226 in this background fully restored FLI1 and LRRF1 localization." (PMID 39404459, 2024). "Our results also indicate an LRRF1-independent localization mechanism for FLI1, which likely influence their mechanism(s) of action during chlamydial infection." (PMID 39404459, 2024). "This study looks in detail at interactions of two host proteins, FLI1 and LRRF1, during chlamydial infection." (PMID 39404459, 2024). "Two statistically significant hits were the eukaryotic protein leucine rich repeat Flightless-1 interacting protein 1 (LRRF1/LRRFIP1/GCF2) and its binding partner, Flightless-1 (FLI1/FLII), both of which localize to the inclusion membrane during chlamydial infection." (PMID 39404459, 2024).
Chylothorax (1 paper, 2025). The presence of chyle in the thoracic cavity. "Using inducible lymphatic endothelial cell-specific deletion in mice, we demonstrated that combined loss of Erg and Fli1 in adults results in fatal lymphatic failure, including chylothorax, chylous ascites, and impaired lymphatic drainage." (PMID 41460562, 2025).
cognitive deficits (1 paper, 2023). "The inhibition of Fli-1 via antisense oligonucleotide Fli-1 Gapmer decelerates pericyte loss, reduces inflammatory response, ameliorates cognitive deficits, improves BBB function, and decreases Aβ deposition." (PMID 37566011, 2023).
colorectal adenocarcinoma (1 paper, 2019). The most common type of colorectal carcinoma. "FLI1 is also downregulated in intraductal papillary mucinous neoplasms (IPMNs) and in colorectal adenocarcinomas." (PMID 31231464, 2019).
COVID-19 (1 paper, 2021). A disease caused by infection with severe acute respiratory syndrome coronavirus 2. "Consistently, the regulons including GATA2, SPI1, ETS2, FLI1, and ETV6 were activated in COVID-19 patients." (PMID 34349096, 2021). "Collectively, MkP- and GP-priming TFs, including ETS2, FLI1, SPI1, and GATA2 were activated in the HSC/MPP cells from COVID-19 patients, probably contributing to the increased output of myeloid progenitor cells and decreased output of lymphoid progenitors." (PMID 34349096, 2021). "In addition, we conducted score analysis to examine the transcriptional level of TF-downstream target genes, and identified substantial increase in scores of ETS2, FLI1, and SPI1 in COVID-19 patients compared with controls." (PMID 34349096, 2021). "Regarding the MkP-priming TFs, significant co-expression of ETS2-FLI1-GATA2-PBX1 and SPI1-LMO4 was observed in the HSC/MPPs from COVID-19 patients, with 75.8% and 61.4% of HSC/MPPs co-expressing ETS2 and FLI1 in the mild and severe cases, respectively, compared with 8.4% in HC." (PMID 34349096, 2021). "Up-regulation of ETS2, FLI1, GATA2, and ETV6 in the HSC/MPPs of COVID-19 patients raised the speculation that the HSC/MPPs preferentially differentiated into MkP cells." (PMID 34349096, 2021).
cyst (1 paper, 2023). A sac-like closed membranous structure that may be empty or contain fluid or amorphous material. "Immunohistochemical staining including factor VIII, podoplanin, endothelial markers (CD31, CD34, ERG avian V‐ets erythroblastosis virus E26 oncogene homolog), FLI1 (“friend leukemia factor”), and matrix metalloproteinase‐1 (MMP-1) can help to identify cAS in the cyst walls." (PMID 35543776, 2023).
dementia (1 paper, 2022). Loss of intellectual abilities interfering with an individual's social and occupational functions. "To specifically enrich our samples in endothelial cells and microglia, with their important role in dementia and white matter disease, we immunolabeled the nuclei using an antibody against ERG/FLI1 (EPR3864) and FACS sorted these cells." (PMID 35543222, 2022).
diabetes (1 paper, 2023). "The development of diabetes is associated with profound inhibition of Fli1 in vascular tissues, while exposure of these rats to high salt levels activates TGF-β and suppresses the expression of Fli1." (PMID 36768203, 2023).
dysplasia (1 paper, 2019). A usually neoplastic transformation of the cell, associated with altered architectural tissue patterns. "We analyzed stomach tissues from 98 patients [8 normal mucosa, 8 intestinal metaplasia (IM), 7 dysplasia, 91 GC] by immunohistochemistry for FLI1." (PMID 31231464, 2019).
esophageal cancer (1 paper, 2018). A primary or metastatic malignant neoplasm involving the esophagus. "For example, most of the genes on the trunk of sample ESCC12 (CCND1, EGFR, APC, TGFBR2, XPC, XPA, FLI1, and NUMA1) have been identified and initially reported on the esophageal cancer." (PMID 30540749, 2018).
follicular lymphoma (1 paper, 2024). Follicular lymphoma is a form of non-Hodgkin lymphoma characterized by a proliferation of B cells whose nodular structure of follicular architecture is preserved. "However, in lymphoblastic and follicular lymphomas, uniformly strong and diffuse or extremely low contrast FLI-1 expression was observed." (PMID 38280044, 2024).
gastric adenocarcinoma (1 paper, 2019). "We also tested if gastric adenocarcinoma cell lines show loss of FLI1 expression, similar to our in vivo observations." (PMID 31231464, 2019). "We recently reported the progressive downregulation of cancer-related genes by CpG methylation in gastric carcinogenesis, and found that FLI1 gene hypermethylation was associated with reduced transcription in gastric adenocarcinoma tissues." (PMID 31231464, 2019). "Our results show that FLI1 is commonly lost in gastric adenocarcinomas, but methylation of FLI1 promoter and loss of expression may be a surrogate marker for global methylation rather than having a functional role in gastric tumorigenesis." (PMID 31231464, 2019). "In our previous study where we analyzed the TCGA gastric adenocarcinoma dataset, we showed that FLI1 was methylated in gastric adenocarcinomas, and its expression was inversely correlated with its level of methylation." (PMID 31231464, 2019). "By RNA analysis, only rare gastric adenocarcinoma cell lines showed FLI1 expression, with FU97 showing the highest level of expression." (PMID 31231464, 2019). "However, most gastric adenocarcinomas showed weak nuclear FLI1 staining with an overall mean H-score of 108.2, which was significantly lower than normal stomach glands (P = 1.2×10-5), intestinal metaplasia (P = 1.4×10-6), and low-grade dysplasia (P=0.006)." (PMID 31231464, 2019). "We previously reported that there was decreased FLI1 RNA in gastric adenocarcinoma tissues as compared to intestinal metaplasia, which inversely correlated with FLI1 promoter methylation levels, but the cellular localization of FLI1 in cancer tissues has not been determined." (PMID 31231464, 2019). "Since we previously found decreased transcription of FLI1 in gastric adenocarcinoma tissues, we hypothesized that FLI1 may act as a tumor suppressor and that its expression would decrease in the progression of gastric carcinogenesis from normal epithelium to dysplasia and adenocarcinoma." (PMID 31231464, 2019). "To assess if FLI1 has a functional role in gastric adenocarcinoma, we overexpressed either control plasmid or FLI1 in AGS cells by lentiviral transduction, and determined the effect of FLI1 expression on invasion and proliferation." (PMID 31231464, 2019). "However, the majority of gastric adenocarcinoma cell lines do not express FLI1, which is in agreement with our results from IHC on primary human samples." (PMID 31231464, 2019). "However, previous studies examining hypermethylation and expression have only analyzed whole tissue, and thus the spatial and cellular distribution of FLI1 in gastric mucosa and in gastric adenocarcinoma cells have not been characterized." (PMID 31231464, 2019). "Additionally, we showed evidence that FLI1 has a functional role in gastric adenocarcinoma, rather than acting as a surrogate marker for global DNA methylation." (PMID 31231464, 2019). "Other commonly used gastric adenocarcinoma cell lines, such as AGS, showed no detectable FLI1 transcription." (PMID 31231464, 2019). "To confirm these findings, we performed a western blot on two gastric adenocarcinoma cell lines that expressed FLI1 RNA (FU97 and NUGC3) and on three gastric adenocarcinoma cell lines that did not (AGS, MKN74, and SNU638)." (PMID 31231464, 2019).
gastrointestinal stromal tumor (1 paper, 2022). "Sarcoma diagnosis relies, not only on morphological and immunohistochemical features, but also on molecular alterations, such as EWS/FLI1 fusion in Ewing sarcoma (EWS), SS18-SSX fusion in synovial sarcoma, or kit mutation in gastrointestinal stromal tumors (GIST)." (PMID 36430703, 2022).
head and neck squamous cell carcinoma (1 paper, 2023). A squamous cell carcinoma that arises from any of the following anatomic sites: lip and oral cavity, nasal cavity, paranasal sinuses, pharynx, larynx, and salivary glands. "The data from the Gene Expression Omnibus (GEO) NPC database and the Cancer Genome Atlas (TCGA) head and neck squamous cell carcinoma (HNSCC) datasets showed that the levels of FLI1 and TIE1 are highly positively correlated." (PMID 36814284, 2023).
hepatic diseases (1 paper, 2023). "Thus, glycyrrhizin used for the treatment of hepatic diseases and itching dermatitis was shown to possess an anti-fibrotic effect in SSc dermal and lung fibroblasts via downregulation of Dnmt1, upregulation of Fli1, and induction of MMP1 gene expression via an ERK1/2-dependent mechanism." (PMID 36768203, 2023).
invasive breast carcinoma (1 paper, 2025). A carcinoma that infiltrates the breast parenchyma. "This study aims to investigate FLI1 expression in invasive breast carcinoma (IBC) and evaluate its association with histopathological grading." (PMID 41300765, 2025). "This study characterized FLI1 protein expression in invasive breast carcinoma and assessed its association with histopathological grade, clinicopathological features, and patient survival." (PMID 41300765, 2025). "While higher FLI1 immunostaining correlated with higher histological grading, FLI1 mRNA levels did not present a significant association with prognostic trends across invasive breast cancer cohort samples." (PMID 41300765, 2025). "This study highlights the potential role of FLI1 in promoting tumor progression and stromal remodeling in invasive breast carcinoma." (PMID 41300765, 2025).
kidney tumor (1 paper, 2025). "Next-generation sequencing (NGS) molecular analysis of the kidney tumor showed a type II EWSR1:FLI1 gene fusion between exon 7 of EWSR1 and exon 5 of FLI1." (PMID 40416106, 2025).
large cell lung carcinoma (1 paper, 2017). "Among the cell lines tested, SCLC cell lines (NCI-H446 and NCI-H1688) and large cell lung carcinoma cell line (NCI-H460) expressed considerably high levels of FLI1." (PMID 28410216, 2017).
liver cancer (1 paper, 2020). An epithelial or non-epithelial malignant neoplasm that arises from the liver. "Fli-1 has been reported to play a role in blood, breast, skin, and liver cancer, particularly in retrovirus-induced hematologic malignancies." (PMID 32210104, 2020).
lymphoblastic lymphoma (1 paper, 2024). A lymphoma composed of immature small to medium-sized precursor lymphoid cells (lymphoblasts). "Only two cases exhibited strong and diffuse FLI-1 expression, as observed in lymphoblastic lymphoma." (PMID 38280044, 2024). "Previous studies have consistently demonstrated FLI-1 overexpression in lymphoblastic lymphoma cases, albeit in small sample groups (88%, 7/8; 92%, 33/36)." (PMID 38280044, 2024). "However, the cause of FLI-1 overexpression in lymphoblastic lymphoma has not yet been elucidated." (PMID 38280044, 2024). "FLI-1 was expressed in a wide variety of hematologic tumors, most frequently in lymphoblastic lymphoma, which was not elucidated previously." (PMID 38280044, 2024). "The expression of FLI-1 can lead to serious diagnostic confusion, especially in small blue round cell tumors, when distinguishing tumors positive for CD99 and CD56 without CD3, CD20, or CD45, such as lymphoblastic lymphoma, PBL, and PCM." (PMID 38280044, 2024).
malignant vascular tumors (1 paper, 2017). "Epithelial cells have been reported to express high levels of Fli-1, a feature that has also been observed in the majority of benign and malignant vascular tumors." (PMID 28418872, 2017).
Merkel cell carcinoma (1 paper, 2017). "Fli-1 expression was also detected in Merkel cell carcinoma." (PMID 28418872, 2017).
mesothelioma (1 paper, 2016). A usually malignant and aggressive neoplasm of the mesothelium which is often associated with exposure to asbestos. "In our case, the papillary or large cell population showed a staining pattern characteristic for mesothelioma with calretinin, cytokeratin, and CD99 positivity, while the small cell component was positive for CD99, WT1, FLI-1, and cytokeratin." (PMID 27403364, 2016).
myasthenia gravis (1 paper, 2023). Myasthenia gravis (MG) is a rare, clinically heterogeneous, autoimmune disorder of the neuromuscular junction characterized by fatigable weakness of voluntary muscles. "However in the GWAS catalog FLI1 has a significant association with Vitiligo, when the onset age is not taken into account, and CTLA4 is found associated with different GWASs (not studied here) for both Myasthenia gravis and Vitiligo." (PMID 37809097, 2023).
myeloid neoplasm (1 paper, 2026). Proliferation of myeloid cells originating from a primitive stem cell. "Our findings expand the spectrum of dmin-associated oncogenic amplifications in myeloid neoplasms and highlight FLI1 and ETS1 as recurrent targets of 11q24-derived ecDNA amplification." (PMID 41982344, 2026).
neuroendocrine tumors (1 paper, 2022). "To analyze the antiangiogenic potential of OCT and PAS on GH3 and GH4C1 cell lines, we used an innovative in vivo platform, that we have recently developed implanting neuroendocrine tumors cells in Tg(fli1:EGFP)y1 zebrafish embryos." (PMID 34128215, 2022).
prostate disease (1 paper, 2019). "Additional genes identified as affected transgenerationally in this study have also been previously associated with prostate disease including Fli1, Egf, Dgk2 and Snai2." (PMID 30778168, 2019). "Several genes previously associated with prostate disease were also identified as affected in the current study: Fli1 (stromal DMR), Egf (epithelial DMR), Dgk2 (stromal differentially expressed mRNA), Snai2 and Cxcl1 (epithelial differentially expressed mRNA)." (PMID 30778168, 2019).
retinoblastoma (1 paper, 2015). A malignant tumor that originates in the nuclear layer of the retina. "Using the fli1:EGFP transgenic zebrafish, the detailed process of intravasation of retinoblastoma cells could be studied." (PMID 26169357, 2015).
sarcoidosis (1 paper, 2023). Sarcoidosis is a multisystemic disorder of unknown cause characterized by the formation of immune granulomas in involved organs. "Unlike myofibroblasts and ECM fibroblasts which enriched fibroblast activation TFs, such as GLIS1 and TRPS1, only in sarcoidosis, endothelial fibroblasts showed enrichment of FLI1, a fibroblast activation suppressor TF, and GATA2, an endothelial cell TF, strictly in sarcoidosis." (PMID 37576111, 2023).
seminoma (1 paper, 2024). A radiosensitive malignant germ cell tumor found in the testis (especially undescended), and extragonadal sites (anterior mediastinum and pineal gland). "Complex i12p cases were all seminomas with recurrent focal loss at 11q24.3 encompassing the ETS transcription factor FLI1." (PMID 39461959, 2024).
Solid Pseudopapillary Neoplasm of the Pancreas (1 paper, 2016). A low-grade malignant neoplasm that arises from the exocrine pancreas. "Eighteen cases of solid pseudopapillary neoplasms of the pancreas were evaluated for RNA expression levels of FLI1, DKK1, INPP5D (SHIP1), IGFBP3, PBK (TOPK), and BCL9 and BCL9L." (PMID 27539223, 2016).
T-cell leukemia (1 paper, 2022). A malignant disease of the T-lymphocytes in the bone marrow, thymus, and/or blood. "We confirmed that CPT could reduce Fli-1 protein expression in the murine T cell leukemia line EL4, which was associated with reduced cell growth and increased apoptosis." (PMID 36074578, 2022).
Thrombocytosis (1 paper, 2024). Increased numbers of platelets in the peripheral blood. "For instance, the haploinsufficient gene coding miR145 through the consequent upregulation of Friend leukemia virus integration 1 (Fli1) gene enables the effective megakaryopoiesis and results in thrombocytosis." (PMID 39544295, 2024).
thymic lymphoma (1 paper, 2013). "It was found that all primary and secondary Fli-1 pre-T LBL as well as a radiation-induced thymic lymphoma contained type 1 5′ Notch1 deletions." (PMID 23667468, 2013).
thyroid angiosarcomas (1 paper, 2024). "By immunohistochemistry, thyroid angiosarcomas are strongly and diffusely positive for pan-endothelial markers, i.e., CD31, CD34, FLI-1 and ERG, but lack expression of thyroid-related immunomarkers including thyroglobulin, TTF1 and PAX8." (PMID 39422760, 2024).
type 2 diabetes (1 paper, 2023). "Interestingly, the crosstalk between Fli1 and TGF-β profibrotic signaling via PKC-δ has previously been described, for example, in type 2 diabetes during salt loading." (PMID 36768203, 2023).